MSLN (mesothelin)
Diseases named in the same sentence as MSLN in open-access papers (continued):
Sharing a sentence is not in itself a finding about the gene and the disease.
pancreatic cancer (continued). "The cell binding of the MSLN/CD3 bsAb was tested on MSLN-negative cell line A431, MSLN-overexpressing A431 cells (named H9), and MSLN-positive pancreatic cancer cell lines KLM-1 and T3M4, as well as different subsets of T cells (PBMC、NKT、γδT)." (PMID 39995672, 2025). "The amount of apCAF (CD74+, PDGFα+) in pancreatic cancer was positively correlated with MSLN expression (P = 0.0026), but were negatively correlated with the amount of effector immune cells such as CD8+ T cells (p = 0.0165) and IFN‐γ+CD4+ T cells (p = 0.0014)." (PMID 39887656, 2025). "Similar findings were reported in ovarian and pancreatic cancers, underscoring the involvement of MSLN." (PMID 41335396, 2025). "Next, we assessed the activity of MSLN-CAR T cells co-cultured with HSV-MSLN-infected pancreatic cancer cells." (PMID 40366419, 2025). "When simultaneous immunohistochemical staining for IMP3 and mesothelin was performed on pancreatic cancer, chronic pancreatitis, and normal pancreatic tissues, the sensitivity was 85% and specificity was 90%." (PMID 40722532, 2025). "In this context, a thorium-227 conjugated Ab, BAY2287411, was developed and evaluated in patient-derived xenograft models of various MSLN-overexpressing malignancies, including breast, colorectal, lung, ovarian, and pancreatic cancers." (PMID 41335396, 2025). "In the meantime, mesothelin-targeting ADC (DMOT4039A) demonstrated partial responses in a subset of pancreatic cancer patients in a phase I trial, with a manageable safety profile, thereby validating mesothelin as a promising target in pancreatic cancer." (PMID 41154706, 2025). "Overall, these results indicate that targeting MSLN can significantly enhance the infiltration of induced neoantigen specific T cells, thereby enhancing its anti‐tumor efficacy in pancreatic cancer." (PMID 39887656, 2025). "Mesothelin levels were found elevated in a variety of malignancies, including mesothelioma, non‐small cell lung cancer, ovarian cancer, and pancreatic cancer." (PMID 39434498, 2025). "Another study introduces self-activating CAR-NK cells that block TGFβ1 signalling in the TME using a peptide called P6, which targets mesothelin in pancreatic tumours." (PMID 40650066, 2025). "No binding was observed on the negative control cell lines which included the human-derived Lewis lung carcinoma cell line (LLC) and the pancreatic carcinoma cell line KLM1 MSLN knockout (KO)." (PMID 40568084, 2025). "Scientists conducted research using anti‐mesothelin CAR T cells to target pancreatic cancer cells that express mesothelin." (PMID 39328262, 2024). "Of note, MSLN is also highly expressed in pancreatic cancer, ovarian cancer, and NSCLC, and thus, most of the clinical trials have included other tumor types as well as MPM." (PMID 39796666, 2024). "On a parallel note, CAR-NK therapy targeting MSLN has demonstrated strong cytotoxicity in pancreatic cancer cells." (PMID 38694508, 2024). "Enhanced pancreatic tumor metastasis due to Akt signaling and mitochondrial respiration has been reported in mice with overexpression of mesothelin." (PMID 38396817, 2024). "Based on these results, a Phase I trial was initiated where the treatment of one patient with advanced pancreatic cancer with anti-mesothelin resulted in almost complete tumor disappearance 240 days post IV infusion of 7 × 19 CAR-T cells." (PMID 38339310, 2024). "MSLN promoted biological behaviors of pancreatic cancer cells, such as intercellular-matrix adhesion, proliferation, migration and invasion." (PMID 38628720, 2024). "Our results showed that up-regulation of MSLN was accompanied with the expression changes of E-Cadherin, Vimentin and Snail in pancreatic cancer cells, hence promoting EMT." (PMID 38628720, 2024). "MSLN overexpression was previously reported to induce resistance to treatment in pancreatic cancer cells." (PMID 38954005, 2024).
pancreatic cancer (continued). "In a phase III clinical trial on patients with advanced pancreatic cancer that expressed glypican-1 or mesothelin, anti-mesothelin-7*19 CAR-T therapy resulted in near complete tumor eradication at 240 days after intravenous infusion." (PMID 38756774, 2024). "Based on MSLN KO and OE models, we performed a variety of experiments to investigate potential effects of MSLN on intercellular-matrix adhesion, proliferation, migration, invasion and chemoresistance of pancreatic cancer cells." (PMID 38628720, 2024). "Mesothelin overexpressed in pancreatic cancer activates Akt signaling, which is reported to stimulate mitochondrial respiration." (PMID 38396817, 2024). "In line with the in vitro results, in vivo assay using a pancreatic tumor mouse model with IP injected AsPC-1 cells also demonstrated the stronger anti-tumor activity of ACOD1-/- MSLN-CAR-iMACs." (PMID 37723178, 2023). "Second, MSLN was identified as a tumor-differentiation antigen with an overexpression discovered in multiple cancer types, such as epithelial mesothelioma, pancreatic cancer, and lung adenocarcinoma." (PMID 36701413, 2023). "Despite immunophenotypic differences, CD28ζ and 4-1BBζ CAR T-cells demonstrated similar efficacy in real-time cytotoxicity assays against the pancreatic cancer cell line, Capan2, which expresses MSLN natively with > 95% tumour cell lysis at 48 h." (PMID 38105188, 2023). "CA-125 also binds with mesothelin, a protein expressed by ovarian, lung, and pancreas cancers, in the normal mesothelium." (PMID 37792745, 2023). "In this study, mesothelin was overexpressed on the human pancreatic cancer cell line MIA PaCa-2, and the resulting cell line was sensitized to the anti-mesothelin ADC." (PMID 37880707, 2023). "Another selected target was mesothelin (MSLN), which is overexpressed by a large number of pancreatic cancers." (PMID 37629147, 2023). "Mesothelin (MSLN) is a glycosylphosphatidylinositol (GPI)-anchored cell surface protein which is overexpressed in ~85% of human pancreatic cancer cells and clinical specimens." (PMID 37631252, 2023). "CAR-Ms targeting MSLN show increased phagocytic activity against ovarian/pancreatic cancer cells expressing MSLN." (PMID 35410257, 2022). "The pancreatic cancer patients’ Cf-MSLN abundance was significantly decreased with respect of the control groups (from 0.93 ± 0.13 to 0.74 ± 0.20)." (PMID 36009489, 2022). "The target antigens in multiple early-phase CAR T-cell clinical trials for pancreatic cancer include mesothelin (MSLN), prostate stem cell antigen (PSCA), carcinoembryonic antigen (CEA), HER2, MUC1, and CD133." (PMID 36290818, 2022). "Listeria monocytogenes expressing mesothelin are potential vaccines for preventing pancreatic cancer metastasis." (PMID 35814712, 2022). "In pancreatic cancer, miR-198 was determined to be a key player in a regulatory feedback loop with mesothelin, wherein mesothelin represses miR-198 through OCT-2 induction mediated by NF-κB." (PMID 35326701, 2022). "Carcinoembryonic antigen (CEA) and mesothelin (MSLN) were highly expressed in pancreatic cancer, and dual-receptor CAR T cells targeting both antigens were found to target tumor sites precisely and reduce tumor load in pancreatic cancer mouse models." (PMID 36341440, 2022). "This Ab elicited antibody-dependent cellular cytotoxicity (ADCC) on pancreatic cancer cells in vitro and blocked the interaction between MSLN and its ligand CA125/MUC16." (PMID 35892707, 2022). "Matsuzawa and collaborators also showed that MSLN blockade by Amatuximab increases c-met expression, another CSC marker, in pancreatic cancer cell lines, suggesting an indirect link between MSLN and the CSC phenotype." (PMID 35162954, 2022). "In a clinical study on a small group of ovarian and pancreatic cancer patients, an 89Zr-labeled anti-MSLN Ab detected the majority of malignant lesions with minimal non-specific uptake." (PMID 35836956, 2022).
pancreatic cancer (continued). "Mesothelin overexpression in pancreatic cancer cells leads to the constitutive activation of NF-κB, thereby increasing the production of IL-6 and enhanced tumor cell proliferation and survival via auto/paracrine IL-6/sIL-6R trans-signaling." (PMID 35326701, 2022). "Some cancers have several studies with the same target, such as hepatocellular carcinoma with GPC3, pancreatic cancer with MSLN, and glioma with GD2." (PMID 35681646, 2022). "A further immunotherapeutic target is the mesothelin (MSLN) glycoprotein that is specifically expressed on the surface of mesothelial cells and overexpressed in most pancreatic cancers." (PMID 35214685, 2022). "The most experience with CAR T cells in PDAC patients has been with targeting mesothelin since approximately 80% of pancreatic carcinomas express mesothelin and, as a result, has become a key target for CAR T cell therapy trials (NCT03323944)." (PMID 35844304, 2022). "In the present study, we demonstrated significant effects of Amatuximab by mesothelin blockage in pancreatic cancer cells." (PMID 33637083, 2021). "In our results, we concluded that MET was the important factor in the effects of Amatuximab by mesothelin blockage in pancreatic cancer cells." (PMID 33637083, 2021). "Mesothelin is highly overexpressed in various types of cancers, such as mesothelioma, ovarian and pancreatic cancer." (PMID 33637083, 2021). "LGA-PEI was covalently conjugated with a single-chain variable fragment antibody (scFv) against mesothelin (MSLN), a biomarker for pancreatic cancer (PC), or a special Ab fragment crystallizable region-binding peptide (FcBP), which binds to any full Ab (IgG)." (PMID 34577541, 2021). "In our study, the mesothelin blockage by Amatuximab directly suppressed the expression level of pMET and led to suppression of malignant features of AsPC-1 and Capan-2 pancreatic cancer cells." (PMID 33637083, 2021). "We discover the role and potential mechanism of mesothelin blockage by Amatuximab in human pancreatic cells both expressing high or low level of mesothelin in vitro experiment and peritonitis mouse model of pancreatic cancer." (PMID 33637083, 2021). "To validate the efficacy of Amatuximab for pancreatic cancer cells and the relationship between effect of Amatuximab and expression of mesothelin, we need to perform the experiment using other several pancreatic cancer cell lines." (PMID 33637083, 2021). "Another group used PDAC cell lines and CR-cultured primary cells to identify the role of the low-immunogenicity anti-mesothelin immunotoxin RG7787 in pancreatic cancer." (PMID 34150763, 2021). "In a recent pre-clinical trial, a novel replication-defective recombinant adenovirus 40 (rAd40) expressing mouse mesothelin (Msln) was administrated intravenously in mouse models as a prophylactic cancer vaccine against metastatic lesions of pancreatic cancer." (PMID 34681560, 2021). "To evaluate the antitumor efficacy of gene-edited CAR-T cells in vivo, we used NPG mice (Vital Star) bearing CRL5826-PD-L1 tumors (CDX) and two patient-derived tumor xenograft (PDX) models derived from pancreatic cancer samples that were both MSLN positive." (PMID 34381179, 2021). "A VLP-based on SHIV VLPs with murine MSLN displayed on the surface of the particles was used to immunize mice harboring pancreatic tumor cells." (PMID 33632278, 2021). "We next examined the effects of blockade of mesothelin by Amatuximab on the proliferation of pancreatic cancer cells." (PMID 33637083, 2021). "Tissue markers that are differentially expressed in pancreatic cancer (CEA, mucin-1 (MUC-1)), mesothelin, mutated KRAS G12, CA19-9, carcinoembryonic antigen-related cell adhesion molecule 6 (CEACAM6) have been recently studied as potentials vaccine targets." (PMID 33546207, 2021).
pancreatic cancer (continued). "Other studies have evaluated the feasibility of various chimeric antigen receptor (CAR)-modified T cells recognising antigens such as mesothelin and glypican-1 in solid tumours including pancreatic cancer." (PMID 33917882, 2021). "Anti-PSCA CARs induced larger amounts of IFN-γ than did anti-MSLN CARs when co-cultured with pancreatic cancer cell lines." (PMID 35582441, 2020). "Positive outcomes have been observed after using CAR-T cell therapy targeting MSLN in lung, breast, and pancreatic cancers." (PMID 32560392, 2020). "Concerning the use of CAR-T against MSLN in human pancreatic cancer, a phase I clinical trial was completed (NCT01897415) in March 2017." (PMID 35582441, 2020). "MSLN is highly expressed in pancreatic ductal adenocarcinoma, the most common subtype of pancreatic cancer." (PMID 32605175, 2020). "In ovarian and pancreatic cancers, the role of MSLN in tumor progression/invasion has been associated to MUC16 (CA125), the only described binding partner of MSLN." (PMID 32612258, 2020). "MSLN-targeting CAR-T cells engineered by the piggyBac transposon system have been proven to be cytotoxic to pancreatic cancer cells and bile duct carcinoma cells." (PMID 31463062, 2019). "It was an inspiration for making in vivo studies on the effectiveness in targeting the pancreatic carcinoma cells in mouse xenografts by SPIONs coupled with anti-mesothelin antibodies." (PMID 30791358, 2019). "Our established epitope peptide-specific CTL clones responded to pancreatic cancer cells that endogenously expressed mesothelin in an HLA-A24-restricted manner." (PMID 30140382, 2018). "In this study, T cells in which meso-CAR expression was induced were able to eliminate metastases arising from pancreatic cancer, indicating that mesothelin is an effective target for the treatment of late-stage, malignant metastatic tumors." (PMID 29568387, 2018). "Mesothelin is overexpressed in infiltrating pancreatic cancer cells and plays an important role in the invasion and migration processes." (PMID 30140382, 2018). "Mesothelin is a promising target for peptide-based immunotherapy for patients with pancreatic cancer." (PMID 30140382, 2018). "To identify pancreatic cancer derived cell lines naturally expressing robust levels of mesothelin, we analyzed AsPC-1, BxPC-3, Panc-1 and MIA Paca-2 cell lines." (PMID 30333914, 2018). "In the present study, we focused on mesothelin as a novel tumor-specific antigen target for anticancer immunotherapy for pancreatic cancer." (PMID 30140382, 2018). "CARs specific for mesothelin have been investigated in clinical trials to treat patients with pancreatic cancer and malignant pleural mesothelioma." (PMID 29568411, 2018). "A phase I study of SS1P given as a bolus i.v. infusion to 2 patients with mesothelin-expressing pancreatic cancers was published in 2007 showing safety and feasibility but, unfortunately, no clinical response." (PMID 29474384, 2018). "Mesothelin is a glycoprotein over-expressed on a variety of tumor cells including pancreatic cancer." (PMID 30319627, 2018). "These CTL clones also had specific cytotoxic activity against HLA-A*2402-positive pancreatic cancer cells that endogenously expressed mesothelin." (PMID 30140382, 2018). "Mesothelin is a cell surface glycoprotein whose expression is restricted to a variety of cancer types, including pancreatic cancer." (PMID 30333914, 2018). "The peptide-specific CTL clones also exhibited peptide-specific IFN-γ production against HLA-A*2402-positive pancreatic cancer cells that endogenously expressed mesothelin." (PMID 30140382, 2018). "In this study, we focused on mesothelin as a tumor-specific antigen target for a pancreatic cancer vaccine." (PMID 30140382, 2018). "First, we demonstrated that the pancreatic cancer cell line AsPC-1 highly expressed the integrin αvβ3 and MSLN, and the target cells were genetically engineered to express the red fluorescent protein (RFP)." (PMID 29558951, 2018).
pancreatic cancer (continued). "In the terms of persistence, patients with pancreatic cancer have been treated with T cells that simultaneously express two CARs targeting mesothelin and CD19 in clinical trials." (PMID 29568411, 2018). "Overexpression of mesothelin has been identified in a number of human cancers e.g mesothelioma, lung cancer, colorectal cancer, ovarian cancer as well as pancreatic cancer." (PMID 29854291, 2018). "Several antigens including CEA, HER2, MUC1, CD133, prostate stem cell antigen (PSCA) and mesothelin are prominent targets using this approach in pancreatic cancer." (PMID 30319627, 2018). "The virus with the newly isolated MSLN-targeted OAd showed dramatic selectivity for MSLN-expressing pancreatic cancer cells in vitro and in vivo." (PMID 29614005, 2018). "Mesothelin, which is overexpressed in pancreatic cancer and other solid tumors, is a potential target for pancreatic cancer immunotherapy." (PMID 29568387, 2018). "Together, these results strongly support the general pro-carcinogenic role of MSLN, which is supported by clinical observations that show a linkage between MSLN expression and tumorigenesis in lung, breast, and pancreatic cancers." (PMID 28288645, 2017). "Our LC-MS/MS identified the secreted isoform of MSLN which is capable of binding to CA125/MUC16, a heavily glycosylated membrane-associated protein which is overexpressed on the surface of pancreatic cancer cells." (PMID 28632775, 2017). "Mesothelin is reported to be over-expressed in pancreatic cancer cells, so we assessed mesothelin expression in the Panc02 murine pancreatic adenocarcinoma line." (PMID 26931187, 2016). "In pancreatic cancer, reconstitution of miR-198 resulted in reduced tumor growth and metastasis through direct targeting MSLN, PBX-1, and VCP." (PMID 26852230, 2016). "MSLN is an attractive candidate as a molecular target for pancreatic cancer marker-specific imaging or immunotherapy." (PMID 25883990, 2015). "Overexpression of mesothelin has also been identified in several types of cancer, including mesothelioma, ovarian cancer and pancreatic cancer." (PMID 25789005, 2015). "Mesothelin is a tumor differentiation antigen expressed by epithelial tumors, including pancreatic cancer." (PMID 26536664, 2015). "RG7787 (anti-mesothelin recombinant immunotoxin) is highly cytotoxic to pancreatic cancer cell lines, but with limited activity in vivo." (PMID 26111884, 2015). "We therefore developed a zirconium-89 (89Zr) labeled anti-mesothelin antibody (89Zr-AMA) to study its biodistribution in human pancreatic tumor bearing mice." (PMID 26536664, 2015). "For instance, mesothelin was found with high expression in pancreatic cancer and listeria monocytogenes-expressing mesothelin boost vaccine has been recently reported to increase clinical response and survival in pancreatic patients." (PMID 26329277, 2015). "In in vitro and ex vivo immunochemical studies, we demonstrated specificity of 11-25 mAb to membranous MSLN expressed on several pancreatic cancer cells." (PMID 25883990, 2015). "We have previously reported that the serum level of N-ERC/mesothelin correlated with tumor size in mice with transplanted rat pancreas cancer cells (634NOD cells)." (PMID 25347530, 2014). "The median plasma MSLN concentration in 32 pancreatic cancer patients was 27.4 ng/ml, with the minimum of 3.7 ng/ml and maximum of 101 ng/ml." (PMID 24520352, 2014). "Although absolute numbers were small, patients with primary ovarian or pancreatic cancers, two tumor types known to express mesothelin had relatively higher rates of mesothelin positivity than those with other malignancies." (PMID 25505814, 2014). "Again, we didn’t observe any association between circulating plasma MSLN levels and CD4+ T cell responses in pancreatic cancer subjects at the time point analysis." (PMID 24520352, 2014). "MSLN is expressed in more than 90% of pancreatic tumour tissues as demonstrated by immunohistochemistry." (PMID 24520352, 2014).